SMPD1 (sphingomyelin phosphodiesterase 1)
Diseases named in the same sentence as SMPD1 in open-access papers (continued):
Sharing a sentence is not in itself a finding about the gene and the disease.
tumor (81 papers, 2009 to 2025). "Genes such as ACER1, ASAH1 and SMPD1 exhibit significant differences in expression between tumour and normal tissues." (PMID 40159631, 2025). "Surprisingly, the antidepressant fluoxetine inhibits sphingomyelin phosphodiesterase 1 (SMPD1), the key enzyme for sphingolipid biosynthesis, and tumor progression in patient-derived GBM orthotopic xenograft models." (PMID 37108511, 2023). "We compared mRNA expression levels of SMPD1 in both tumor (TCGA) and normal tissue samples (from TCGA + Gtex)." (PMID 37246980, 2023). "Down-regulation of SMPD1 was observed in tumor specimens compared with normal specimens in several data sets." (PMID 32273521, 2020). "We chose to evaluate this using ECs as a model system since they express ~20 fold more SMPD1 than tumor cells." (PMID 32221387, 2020). "Our studies show that miR-15a targets SMPD1 in ECs and inhibition of miR-15a decreases EC and tumor cell proliferation, enhances cell death and diminishes tumor growth in a mouse CT26 colorectal carcinoma flank tumor model." (PMID 32221387, 2020). "SMPD1 gene that regulates ‘ceramide sphingosine-1-phosphate rheostat’ drives tumor growth and immune escape in non-small cell lung cancer." (PMID 32616845, 2020). "In early investigations, by comparing SMPD1 activity and tumor cell apoptosis rates, the appropriate radiation dosage for CRC radiotherapy could be selected." (PMID 39898245, 2025). "Endothelial SMPD1 has been shown to regulate tumor responses to radiation therapy." (PMID 32221387, 2020). "Furthermore, we found SMPD1 expression in tumor cells; the staining showed a polarized appearance towards the basolateral side of the epithelial layer." (PMID 31049165, 2019). "Extracellularly oriented ceramides produced by acid sphingomyelinase (sphingomyelin phosphodiesterase 1, SMPD1) in lipid rafts activate membrane receptor clustering with different tumor necrosis factors triggering strong apoptotic signal responses." (PMID 39723240, 2024). "An important additional finding describes the strong similarity in expression pattern between SMPD1 and CD68 for cells of the monocyte/macrophage lineage at the tumor site." (PMID 31049165, 2019). "Altogether, the significant differences in the expression of CerS2, CerS6, DEGS2, SMPD1, and UGT8 sphingolipid genes in tumor tissue go hand in hand with elevation of ceramide levels." (PMID 26528430, 2015). "Tumor status induced a significant increase in the expression of CerS2 (p < 0.0001), CerS6 (p < 0.0001), DEGS2 (p < 0.0001), SMPD1 (p < 0.05), and CLN3 (p < 0.0001); and a significant decrease in the expression of UGT8 (p < 0.0001) compared with expression in the corresponding non-tumor tissue." (PMID 26528430, 2015).
infection (49 papers, 2011 to 2025). The state of being infected such as from the introduction of a foreign agent such as serum, vaccine, antigenic substance or organism. "Future studies should pay specific enthusiasm on the potential implications of SMPD1 splice-isoform profiles as a supporting parameter to identify conditions of systemic inflammation in critically ill and associated blood stream infection." (PMID 25898364, 2015). "The result showed that during ALV-J infection, the levels of ASAH1, NAAA, CHKA, PGS1, SGPP1, DEGS2, and SMPD1 genes were significantly increased with infection time." (PMID 38598912, 2024). "Regarding liver biotransformation capacity, our present study revealed that the activity as well as the mRNA and protein expression of selected and important CYP enzymes were less impaired in SMPD1+/− mice at 24 h after induction of polymicrobial infection as compared to wild-type animals." (PMID 30326559, 2018). "Similarly, we did not observe changes in the expression of the lysosomal enzymes ASAH1 and SMPD1 which could account for the increased Cer and/or Sph levels upon infection." (PMID 40249190, 2025). "Therefore, over the course of the 30 h infection, dynamic changes, including metabolization (e.g., to Sph by acid ceramidases [ASAH1], or SM by SMase [SMPD1]) can affect the outcome of our end-point analysis." (PMID 40249190, 2025).
cancer (44 papers, 2006 to 2026). A tumor composed of atypical neoplastic, often pleomorphic cells that invade other tissues. "While there is limited work exploring NK cell function in SMPD1-deficient cancers, studies have suggested that upon SMPD1 knockdown, NK cell effector function was significantly enhanced." (PMID 41139700, 2026). "It has been demonstrated that this drug has anti-cancer activity owing to its ability to inhibit the sphingomyelin phosphodiesterase 1 (SMPD1) enzyme." (PMID 41012454, 2025). "We first evaluated the expression of SMPD1 in human cancers and asked if the levels of SMPD1 correlated with overall survival using the online database KMplotter." (PMID 32221387, 2020). "The L_cancer patient prognosis features and risk score were calculated as: KNG1 × 0.621 + CYP11A1 × 0.600 + SMPD1 × 1.370 + DAND5 × 0.859 + NKPD1 × 0.721 + RP11-59D5_B.2 × 0.568 + CTD-2184C24.2 × 0.514 + RP11-680F8.3 × 0.517 − RP11-51F16.9 × 0.731 + CTD-2012K14.8 × 0.765." (PMID 36419007, 2022). "Proteins such as GDF15, MERTK, MRP2, SMPD-1, GPNMB, GRN, and FSTL1, while less widely recognized, have emerging roles in cancer progression, immune modulation, and metabolic regulation." (PMID 40805206, 2025).
bacterial infections (6 papers, 2011 to 2024). "ASM levels increase with stress, age, and bacterial infections and the downregulation of the ASM gene SMPD1 is associated with resistance to chemotherapy regimens." (PMID 34445706, 2021).
neurodegenerative disease (6 papers, 2021 to 2025). A disorder of the central nervous system characterized by gradual and progressive loss of neural tissue and neurologic function.
liver (2 papers, 2014 to 2024). "Interestingly, correlation analysis in PWS significantly associated Ribokinase (RBKS), KYNU, Macrophage Scavenger Receptor 1 (MSR1), and SMPD1 with metabolic and liver dysfunction markers, such as transaminases, triglycerides, glycemia, and glycated hemoglobin." (PMID 39407757, 2024).
psychiatric disease (2 papers, 2018 to 2024). "The EV inhibitors desipramine and imipramine are used to treat psychiatric disorders and also inhibit acid sphingomyelinase (SMPD1)." (PMID 39330838, 2024). "These so called functional inhibitors of SMPD1 (FIASMA) comprise a broad range of substances, which are frequently prescribed for psychiatric disease entities: desipramine, imipramine, fluphenazine, fluoxetine and amitriptyline, to mention only a few." (PMID 30326559, 2018).
SMPD1 also shares sentences with these, for which no sentence is quoted: multiple myeloma (9 papers); viral infection (9); Obesity (8); cystic fibrosis (7); neurological diseases (7); pancreatic cancer (7); colon carcinoma (6); genetic disorder (6); fibrosarcoma (5); kidney disease (5); Krabbe disease (5); metabolic disorders (5); prostate carcinoma (5); breast carcinoma (4); cardiovascular disease (4); gastric cancer (4); hyperhomocysteinemia (4); Niemann-Pick disease type C (4); alcohol dependence (3); anxiety disorder (3); brain ischemia (3); cholestasis (3); chronic obstructive pulmonary disease (3); glioblastoma (3); glomerulosclerosis (3); Hepatic steatosis (3); Hypertension (3); inflammation (3); neuroblastoma (3); preeclampsia (3).
A further 119 diseases each share a sentence with SMPD1 in 3 papers or fewer.